MYB (MYB proto-oncogene, transcription factor)
Diseases named in the same sentence as MYB in open-access papers (continued):
Sharing a sentence is not in itself a finding about the gene and the disease.
infection (continued). "The transcription factors such as the C2H2 zinc finger, bZIP (basic domain/leucine zipper), WRKY, AP2 (APETALA2)/ERF (ethylene-responsive factor), NAM/ATAF/CUC(NAC), MYB, MYC and bHLH (basic helix–loop–helix), were significantly altered after viroid infection in plants." (PMID 33005494, 2020). "Cla001822 (MYB), Cla016019 (bZIP), Cla016840 (lycopene cyclase), and Cla017696 (ABA insensitive) were continually up-regulated at 0- (control, ck), 1-, and 6-h, slightly down-regulated at 18-h, and up-regulated again at 24- and 48-h post-CGMMV infection." (PMID 30708960, 2019). "The expression of MYB-related TFs was observed after PXO99A infection in CBB23 vs. JG30; OsMYB4 (Os04G0517100) and R2R3-MYB (Os01G0874300 and Os12G0567300) were observed to be upregulated in CBB23 compared with JG30 after PXO99A infection." (PMID 29498672, 2018). "Moreover, at least five transcription factors, such as the oncogene MYB, SMAD family members 6 and 9 (SMAD6 and SMAD9), and histone decetylase 5 (HDAC5), were significantly affected by infection in CHB." (PMID 27197554, 2016). "This aligns with another study, where the establishment of lymphocytic choriomeningitis virus (LCMV)-chronic infection in mice lacking MYB in T cells (Mybfl/flCd4Cre) led to severe immunopathology, with mice typically becoming moribund within 10 days post-infection." (PMID 41232235, 2025). "However, there was no influence on HBeAg and HBsAg levels when MyB was given at 6 and 9 days post-infection." (PMID 39570046, 2024). "Similarly, members of the MYB, bZIP, and NAC TF families, such as MYB44, bZIP10, NAC019, NAC055, and NAC072, are also rapidly induced upon infection, regulating various aspects of the defense response including stomatal closure, immune responses, cell death, and basal defense." (PMID 37828923, 2023). "Thus, MYB mediates the development of CD62L+ TPEX cells and functional exhaustion of CD8+ T cells during the acute phase, sustains long-term proliferative capacity and prevents the attrition of antigen-specific T cells during the chronic phase of infection." (PMID 35978192, 2022). "In our study, AP2/EREBP, NAC, WRKY, MYB and MAPK showed remarkable differential expression in Lxx-infected plants, suggesting the activation of gene networks controlling pathogenesis, disease resistance and growth and development, which tallies well with the growth variation following Lxx infection." (PMID 33529190, 2021). "Before the pathogen infection, plants inoculated with strain PsJN showed partial activity of auxin, ET, brassinosteroids (BR), and JA signaling; as well as regulation of genes related to the cell wall; redox state; peroxidases, signaling, PR proteins and ERF, WRKY and MYB TFs." (PMID 31437216, 2019). "Many transcription factors (MYB, WRKY, F-box domain containing protein, transcription factor Jumonji), defence related genes (TMV induced protein 1–2, NBS-LRR resistance protein) and different types of kinases show altered gene expression during PSTVd infection." (PMID 26937634, 2016). "The expression trend of MYB and NAC family members was not consistent, and the highest expression levels of all WRKY TFs were observed in W. DEGs of WRKY families were more highly expressed in varieties susceptible to FBS infection, which was why we constructed the correlation of WRKY and PRGs." (PMID 36232919, 2022).
hematologic malignancies (7 papers, 2010 to 2024). "Dysregulation of MYB activity is often associated with various hematological disorders." (PMID 35136029, 2022). "And we found that MYB could be a direct drug target of RSL3 and RSL3 is a potent MYB inhibitor that can be used to treat MDS and other hematopoietic diseases." (PMID 38956026, 2024). "Among the downregulated master regulators, MYB and BCL11A have been related to immune system regulation in hematologic malignancies, suggesting their participation in the maintenance of the hematopoiesis and in the regulation of other downregulated master regulators such as IKZF1." (PMID 32260546, 2020).
CNS tumors (5 papers, 2021 to 2024). "In this report, we explore a series of 14 consecutively collected cases, obtained from the NCI CNS tumor clinical consultation service, where we examine MYB(L1) alterations in detail." (PMID 39422766, 2024). "Whether in-frame fusion or truncation, most MYB-rearrangement cases showed high levels of MYB expression, when compared within an archival cohort of > 1000 CNS tumor cases profiled in the course of clinical testing on the same RNA Exome platform." (PMID 39422766, 2024). "Overall, further investigation of the various types of MYB/MYBL1 alterations and their role in CNS tumor development is needed to precisely characterize these tumors and their clinical behavior." (PMID 39422766, 2024).
bacterial infection (3 papers, 2020 to 2024). "Upregulations of genes encoding proteins involved in secondary metabolism, as well as participation of selected WRKY, NAC, MYB, and bHLH TFs in plant response to bacterial infection were notable." (PMID 39524930, 2024). "The response to these agents was mainly associated with the following TF families: GATA (light); WRKY (SA, bacterial infection, chitin); bZIP (auxins); MYB-related, WRKY and C2H2 (ABA); MYB-related and MADS box (gibberellins); C2H2 and WRKY (cold); and WRKY and MYB-related (salt stress)." (PMID 35890495, 2022).
haematopoietic cancer (2 papers, 2020 to 2021). "Of all the functional genetic dependencies examined to date, the transcription factor MYB demonstrates the broadest dependency across diverse AML subtypes, as compared to other non-hematopoietic cancers." (PMID 33527899, 2021).
head and neck tumor (2 papers, 2025). "Our findings expand the molecular landscape of rare MYB or MYBL1 fusion-negative AdCC patients and provide a potential therapeutic strategy for this rare head and neck tumor." (PMID 40184085, 2025).
psychiatric disorder (1 paper, 2016). A disorder characterized by behavioral and/or psychological abnormalities, often accompanied by physical symptoms. "We believe that systematic analysis of the target genes regulated by c-MYB might provide further insight into the understanding of the novel biological functions of c-MYB in psychiatric disorders." (PMID 26912258, 2016).
MYB also shares sentences with these, for which no sentence is quoted: mucoepidermoid carcinoma (7 papers); ganglioglioma (5); anaplastic astrocytoma (4); rhabdomyosarcoma (4); breast (3); cyst (3); diffuse midline glioma (3); esophageal cancer (3); hemoglobinopathy (3); lung adenocarcinoma (3); myeloproliferative neoplasm (3); myoepithelioma (3); sinonasal carcinoma (3); T-cell leukemia (3); acute promyelocytic leukemia (2); adenocarcinoma (2); adenoid cystic carcinomas of the breast (2); Alzheimer disease (2); chronic lymphocytic leukemia (2); colitis (2); colorectal tumors (2); embryonal rhabdomyosarcoma (2); embryonal tumor (2); glioneuronal tumors (2); head and neck cancer (2); Hodgkins lymphoma (2); kidney damage (2); mantle cell lymphoma (2); medulloblastoma (2); pilocytic astrocytoma (2).
A further 84 diseases each share a sentence with MYB in 2 papers or fewer.